ICAM1 (intercellular adhesion molecule 1)
Diseases named in the same sentence as ICAM1 in open-access papers (continued):
Sharing a sentence is not in itself a finding about the gene and the disease.
gastric cancer (continued). "Here, we found that the expression of IL-8, NF-kB p65 subunit, CCL20, ICAM1, and beta-catenin as cancer stem cell markers was significant after infection for 24 h of infection, as was observed in the 2-D gastric cancer cells." (PMID 37047540, 2023). "Several articles have suggested that patients with ICAM1-positive tumor cells have better clinical outcomes in breast, colorectal, and gastric cancers." (PMID 36353618, 2022). "In mouse models, CAR-T cells targeting ICAM-1 can target both primary and metastatic gastric cancers, exhibiting a good therapeutic effect." (PMID 36341377, 2022). "Soluble forms of ICAM1 enhance the pro-metastatic phenotype as well as pro-inflammatory and oncogenic signaling in lung and gastric cancer patients." (PMID 34944000, 2021). "ICAM1-targeting therapy has potential application values in the treatment of some malignancies, including thyroid cancer, pancreatic cancer, and gastric carcinoma." (PMID 33072116, 2020). "Surprisingly, an in vivo study in gastric cancer even indicated that ICAM1 possibly inhibits PM formation due to ICAM1/LFA1 mediated mononuclear cell recruitment." (PMID 27074785, 2016). "Comparing with the normal group, the signal densities of cytokines were upregulated in the MNNG-induced gastric cancer groups, including Activin A, Agrin, IL-1α (both P < 0.01), ICAM-1 (P < 0.001), and TIMP-1 (P < 0.05)." (PMID 28119756, 2016). "In this study, serum levels of soluble intercellular adhesion molecule-1 (sICAM-1) and soluble E-selectin (sE-selectin) were determined in patients with gastric cancer." (PMID 9683305, 1998). "Moreover, the cell adhesion pathway modulates gastric cancer cell sensitivity to cisplatin by regulating adhesion molecules such as Muc-1, ICAM-1, and VCAM-1." (PMID 40069421, 2025). "However, the GEPIA analysis revealed that both MAPK1 and ICAM1 were highly expressed in gastric cancer tissues, whereas MAOA expression was relatively low." (PMID 40283909, 2025). "In addition, the upregulation of ICAM1 has been demonstrated in different types of cancer, including lung adenocarcinoma, gastric cancer, breast cancer, melanoma, and oral squamous cell carcinoma, among others." (PMID 39201551, 2024). "HTLV-1 may spread between gastric cancer cells, followed by the combination of intracellular Tax protein expression and the stimulation of ICAM-1 on the cell surface to trigger microtubule organization center polarization." (PMID 39228892, 2024). "The molecular mechanism of action of Les-4367 is associated with the induction of extrinsic and intrinsic apoptotic pathways, decreased MMP-2 and ICAM-1 concentrations—which are involved in the invasion of gastric cancer—as well as reduced levels of the pro-inflammatory cytokine IL-6." (PMID 37047765, 2023). "ICAM-1 was targeted by miR-147 and thereby affected the cell migration of gastric cancer cells." (PMID 33103723, 2020). "However, in an in vivo study in gastric cancer ICAM-1 is indicated as a possible inhibitor of peritoneal metastasis due to ICAM-1/lymphocyte function-associated antigen 1 (LFA1)-mediated mononuclear cell recruitment." (PMID 32780245, 2020). "Studies have shown that the positive expression rate of ICAM-1 was related with lymph node metastasis and depth of tumor invasion, and the VCAM-1 expression positive gastric cancers were more invasive and were associated with more lymph node metastases than VCAM-1 expression negative ones." (PMID 26847082, 2016). "ICAM-1 could only be detected in carcinoma cells from a few patients with gastric cancer, whereas all of the metastatic carcinoma cells from peritoneal effusions exhibited high ICAM-1 expression." (PMID 26231039, 2015). "The data revealed a gene expression pattern in EBV-positive gastric cancer, highlighting immune response, inflammation, and cell proliferation genes (e.g., GBP4, ICAM1, IL32, TNFSF10)." (PMID 40110195, 2025).
gastric cancer (continued). "To assess the biological function of ICAM1 in GCSCs, we used the CRISPR/iCas9 system to generate an ICAM1 knockout gastric cancer stem cell line (GCSC-ICAM1KO)." (PMID 39201551, 2024). "We evaluated the potential targeting of CD54/ICAM1, a marker of gastric cancer stem cells, with miRNAs to detect GC in blood samples." (PMID 39125490, 2024). "Curcumin inhibits Bcl-2, Bcl-XL, VEGF, c-Myc, ICAM-1, EGFR, STAT3 phosphorylation, and cyclin D1 genes involved in the various stages of breast, prostate, and gastric cancer proliferation, angiogenesis, invasion, and metastasis." (PMID 33178666, 2020). "In our study, serum ICAM-1 and TIMP-1 levels in MNNG-induced gastric cancer were higher than the normal group." (PMID 28119756, 2016). "Serum concentrations of ICAM-1 and VCAM-1 were significantly elevated in the patients with gastric cancer in comparison with the group of healthy subjects (P < 0.00001 and P < 0.0001 respectively)." (PMID 9400933, 1997). "For instance, knocking WISP3 down lessened cell proliferation and migration in GC (gastric cancer), however, WISP3 accelerated chondrosarcoma migration through upregulating ICAM-1." (PMID 37468964, 2023). "In patients with gastric cancer ICAM-1 expression on cancer cells was significantly decreased in patients with lymph node metastasis with the prognosis of patients being poorer in patients with ICAM-1-negative tumors." (PMID 26513172, 2015). "For instance, in gastric cancer cells treated with 60 μg/mL paeonol, the expression of MAPK1 protein was downregulated, while ICAM1 protein expression showed no significant change." (PMID 40283909, 2025). "Our group previously reported a subset of cells lacking CD54/ICAM1 in healthy donors, but present in GC patients, making CD54/ICAM1 a protein of interest in gastric cancer." (PMID 39125490, 2024). "Despite the cross-reactivity of CAR T cells against ICAM-1, we have not observed any significant off-tumor expansion of CAR T cells in our previous xenograft models including systemic ATC 8505C and gastric cancer Hs 746T36,42,49." (PMID 36463361, 2022).
myocardial infarction (62 papers, 2007 to 2026). Gross necrosis of the myocardium, as a result of interruption of the blood supply to the area, as in coronary thrombosis. "Elevated monocyte ICAM1 has been linked to inflammation and vascular injury resulting from myocardial infarction, and elevated ICAM1 in the BMPR2 mutant PAH monocyte had a much greater impact on enhanced adhesion and transendothelial migration than PAH EC." (PMID 40234964, 2025). "Acute myocardial infarction and other coronary syndromes have been linked to ICAM-1 and VCAM-1 in several investigations." (PMID 36408439, 2022). "ICAM-1 is the main receptor for rhinoviruses, which, similar to other viruses causing respiratory infections, are significantly linked to myocardial infarction." (PMID 32852032, 2020). "Similar to CXADR, ICAM-1 is a virus receptor, for rhinoviruses, which cause respiratory infections but have been linked to myocardial infarction." (PMID 32852032, 2020). "For example, the ICAM1 rs5498 polymorphism was reported to be linked to a decreased risk of myocardial infarction (MI)." (PMID 30473535, 2018). "ABO polymorphism increases the susceptibility to myocardial infarction through some pathways, such as increasing vWF level, soluble intercellular adhesion molecule-1 level, soluble P-selectin level, and soluble E-selectin level." (PMID 28811939, 2017). "Podgoreanu and colleagues reported an association of ICAM1 SNP rs5498 with postoperative myocardial infarction." (PMID 17677000, 2007). "In a prospective cohort study designed to evaluate markers of coronary risk, increased plasma levels of ICAM-1 were associated with the risk of myocardial infarction and angina pectoris, indicating circulating levels of ICAM-1 as possible risk markers for future coronary events." (PMID 28050226, 2016). "Elevated ICAM-1 concentration increases the risk of myocardial infarction or coronary death." (PMID 25769179, 2015). "In fact, not only are VCAM-1 and ICAM-1 highly expressed on the endothelium overlaying atherosclerotic lesions, but an increased serum concentration of these molecules is also related to CV risk factors and incident myocardial infarction." (PMID 22962622, 2012). "The FAM5C gene has been associated with myocardial infarction and functional studies have shown that it increases the production of ROS, nuclear factor-kappaB (NF-κB) activity, and expression of the intercellular and vascular cell adhesion molecules, ICAM-1 and VCAM-1." (PMID 29206233, 2017). "ICAM-1 is implicated in neutrophil and monocyte-endothelial cell adhesion, processes contributing to myocardial neutrophil infiltration and microvascular coronary slow flow, both viewed as important to the pathophysiologic responses in acute myocardial infarction (AMI)." (PMID 28881754, 2017). "It has been reported that ICAM-1 is expressed in the blood vessels of mouse ischemic limbs and in the postmortem hearts of patients with myocardial infarction." (PMID 40003604, 2025). "There are studies that have demonstrated the increase in soluble ICAM 1 in the context of acute myocardial infarction, but also its overregulation in human cardiomyocytes after infarction." (PMID 39062865, 2024). "Adipose-derived stem cells conjugated with CD90/ICAM-1-tMBs, known as StemBells, have been proposed as an image-guided treatment for myocardial infarction (MI) and to prevent atherosclerosis acceleration post-MI." (PMID 37376072, 2023). "IL-6, VCAM-1, and ICAM-1 serum levels were assessed in patients with myocardial infarction who were brought to the emergency." (PMID 36408439, 2022). "Our results show that on day 14 of myocardial infarction the expression of ICAM-1 is still elevated." (PMID 30642049, 2019). "In a rat model of acute myocardial infarction, ICAM-1-blocking antibodies increased the recovery of left ventricular developed pressure and reduced coronary vascular resistance." (PMID 30642049, 2019).
myocardial infarction (continued). "Several studies addressed the association between Intercellular adhesion molecule 1 (ICAM-1) rs5498 polymorphism and Myocardial Infarction (MI) risk." (PMID 28881754, 2017). "Patients with an acute myocardial infarction had the highest measures of IL-6 and ICAM-1 as has been reported in previous studies." (PMID 23349778, 2013). "Although the predictive role of ICAM-1 in CVD risk is unclear, it has been associated with future myocardial infarction risk, thus, the mechanism and implications of a postprandial increase in ICAM-1 deserve further study." (PMID 22059644, 2011). "In addition, serum ICAM-1 levels are significantly elevated in patients with acute myocardial infarction." (PMID 40918185, 2025). "Since GXNI treatment of acute myocardial infarction is mainly related to the anti-inflammatory effects mediated by CXCR1-NF-κB-COX-2/ICAM-1/VCAM-1-mediated IL-8 signaling pathway, the release of inflammatory factors and leukocyte infiltration were further examined." (PMID 36325326, 2022). "In conclusion, the combination of transcriptome analysis and subsequent RT-PCR, WB and IHC verification revealed that GXNI has a significant therapeutic effect on acute myocardial infarction in mice mainly via inhibiting the CXCR1-NF-κB-COX-2/ICAM-1/VCAM-1 pathway." (PMID 36325326, 2022). "Furthermore, endothelial expression of leukocyte-recruiting cell surface proteins like ICAM-1 und VCAM-1 is enhanced in Stamp2 deficiency, a mechanism which has been closely linked to myocardial infarct healing und -function." (PMID 34691017, 2021). "Similarly, level of proinflammatory markers (hs-CRP, IL-6, and ICAM-1) and pregnancy associated plasma protein-A (PAPP-A) in serum also clearly display myocardial infarction (MI)." (PMID 25949827, 2015). "Although the physiologic function of soluble ICAM-1 remains to be fully defined, plasma concentration of sICAM-1 have a predictive value for the risk of myocardial infarction, ischemic stroke, peripheral arterial disease and noninsulin-dependent diabetes mellitus in epidemiological studies." (PMID 21533024, 2011). "Frequencies of the K469E variants of ICAM-1 gene in CHD (n=100), unstable angina (UA) (n=27), myocardial infarction (MI) (n=73) and controls (n= 50)." (PMID 20940515, 2010). "AMI: acute myocardial infarction; CRP: C-reactive protein; IL-6: interleukin-6; VCAM-1: vascular cell adhesion molecule 1; ICAM-1: intercellular adhesion molecule-1; ACEi: angiotensin-converting enzyme inhibitors; ARBs: angiotensin II receptor blockers." (PMID 31778438, 2019). "Different from our findings, a small randomized study including 18 patients with acute myocardial infarction assessed the effect of TMZ on plasma ICAM-1 levels, which identified that the plasma ICAM-1 level of the TMZ group was elevated for the first 24 h but decreased in the next two days." (PMID 34259103, 2021). "In case of myocardial infarction, antibodies against matrix metalloproteinase-2 (MMP2) or intercellular adhesion molecule-1 (ICAM-1) could enhance the ability of the microbubbles to increase the effects of imaging and delivery." (PMID 33066531, 2020). "Moreover, aronia berry extract has been shown to reduce blood cardiovascular risk markers such as oxidized-low-density lipoproteins (LDL), C-reactive protein (CRP), IL-6, soluble-ICAM-1, soluble-VCAM-1, and MCP-1 in patients after myocardial infarction." (PMID 31452653, 2019). "TNF-α can up-regulate ICAM-1 expression of MSC and enhance the cells’ migration ability, and it can modify characteristics of MSC to improve their engraftment in experimental myocardial infarction." (PMID 22296115, 2012). "Therefore, ICAM-1 and VCAM-1 are related with the progression of myocardial infarction." (PMID 36408439, 2022).
colorectal cancer (60 papers, 1998 to 2025). A primary or metastatic malignant neoplasm that affects the colon or rectum. "In vivo, ICAM-1 is implicated in the formation of liver metastases from colorectal cancer, and mediates the infiltration of tumour cells into tumour mass." (PMID 32982772, 2020). "Along this line, the presence of ICAM-1 in colorectal cancer has been associated with better prognosis." (PMID 29099772, 2017). "Soluble intercellular adhesion molecule 1 was inversely associated with tumor budding overall (M1: β = −0.57, p = 0.03), among females (M1: β = −0.81, p‐value = 0.03) and later‐onset (≥ 50 years) colorectal cancer (M1: β = −0.71, p‐value = 0.008)." (PMID 40985344, 2025). "Therefore, this study aimed to investigate the improvement effect of NAC on QOE in suppressing colorectal cancer migration and invasion, through the ICAM-1 and MMP-2 associated with iNOS/eNOS suppression." (PMID 37575276, 2023). "In 98 matched colorectal patients, the abundance of F. nucleatum in the tumor tissues of patients with colorectal cancer was correlated with the expression levels of ALPK1 and ICAM1, which were also associated with shorter overall survival time in patients with colorectal cancer liver metastasis." (PMID 36139553, 2022). "ICAM-1 expression on tumor cells has been extensively studied and linked with their ability to invade adjacent and distant organs and with their increased metastatic potential in osteosarcoma, breast or colorectal cancer cells." (PMID 31511625, 2019). "Importantly, tumor-associated fibroblasts in colorectal cancer tissue sections also show increased ICAM-1 expression in comparison to healthy mucosa." (PMID 29099772, 2017). "An immunocompetent Balb/c mouse model was established by using murine colorectal carcinoma CT26 cells stably expressing human ICAM1 (CT26.WT‐hICAM1) owing to the unavailability of mouse ATC cell lines." (PMID 40539828, 2025). "An immunocompetent Balb/c mouse model was established by using murine colorectal carcinoma CT26 cells stably expressing human ICAM1 (CT26-hICAM1) due to low tumor formation rates of mouse cervical cancer cell lines." (PMID 39971940, 2025). "The oncogenic role of ICAM1 in colorectal cancer was recently reported using in vivo and in vitro analyses to demonstrate the migratory, invasive, and angiogenic potential of ICAM1-expressing cells." (PMID 39201551, 2024). "Dysregulation in ICAM-1 expression can be triggered by different pathological events such as Dry Eye Disease, Crohn’s Disease, colorectal cancer, and hepatocellular carcinoma." (PMID 38731980, 2024). "ICAM‐1 promotes tumour relapse and metastasis in colorectal cancer, lymphoma, hepatocellular carcinoma cells and epithelial tumorigenesis." (PMID 37082943, 2023). "In contrast, some studies revealed that upregulation of ICAM‐1 expression reflected low growth potential and good prognosis in breast, gastric and colorectal cancers." (PMID 37082943, 2023). "Colorectal cancer cells, in contrast to normal intestinal epithelial cells, express ICAM-1, which, through interaction with ligands, promotes tumor metastasis." (PMID 37569878, 2023). "For example, in colorectal cancer cells, it has been shown that ICAM-1 can be phosphorylated on its intracellular domain by c-MET, which enables it to act as an adapter protein between c-MET and Src, promoting signaling." (PMID 37237555, 2023). "In this study, ICAM-1 expression was shown to favor migration and invasiveness of colorectal cancer cell lines in vitro, and antibody-mediated blockade of ICAM-1 inhibited lung metastasis in a mouse xenograft model." (PMID 37237555, 2023). "In contrast to the study above, it has also been reported that ICAM-1 expression positively correlates with colorectal cancer stage." (PMID 37237555, 2023).